ENSG00000252992
Synonyms: LOC124900313
Gene: Small Cajal body-specific RNA gene on chromosome 11 (117,263,799 to 117,263,952, forward strand). Ensembl gene ENSG00000252992.
Gene Ontology:
Biological process: RNA processing
Cellular component: Cajal body; nucleolus